TYRO3 (TYRO3 protein tyrosine kinase)
Diseases named in the same sentence as TYRO3 in open-access papers (continued):
Sharing a sentence is not in itself a finding about the gene and the disease.
tumor (continued). "Given the current interest in agonistic anti-CD137 antibodies for cancer treatment, TYRO3 inhibition might be useful for both inhibiting tumour growth and boosting the antitumour immune response." (PMID 30765874, 2019). "We also found that the treatment of established MGH-U3 xenografts in nude mice with intraperitoneal injections of TYRO3 siRNA reduced significantly the tumour growth as compared to in similar tumours treated with a scramble siRNA (≈354 mm3 versus 1090 mm3 at day 21, p < 0.0001)." (PMID 30765874, 2019). "Furthermore, cancer cell-derived ProS1 is a functional activator of Tyro3 and hence can be an autocrine or paracrine supporter of tumour progression." (PMID 31766614, 2019). "GAS6 was more strongly expressed in MIBCs than in NMIBCs, suggesting that GAS6 might increase the autocrine or paracrine activation of TYRO3 in muscle-invasive tumours." (PMID 30765874, 2019). "Moreover, they have clearly identified ProS1 as a tumour-derived, activating ligand of Tyro3 beyond its role in blood coagulation regulation." (PMID 31766614, 2019). "Inhibition of TYRO3 reduces tumor growth and metastasis in animal models." (PMID 30501104, 2018). "The functions of TYRO3 that mediate migration of neurons to the hypothalamus during normal development and changes in platelet shape and adhesion during clot formation likely also promote tumor cell invasion, migration and metastasis." (PMID 30501104, 2018). "Inhibition of TYRO3 in sorafenib-resistant Huh-7 cells using siRNA decreased tumor cell expansion relative to cells expressing a control siRNA and treatment with a combination of sorafenib and siTYRO3 was significantly more effective than either treatment alone." (PMID 30501104, 2018). "Together these data suggest that TYRO3 functions in tumor cells to promote metastasis." (PMID 30501104, 2018). "However, Tyro3 was overexpressed within the tumor in comparison to normal colon mucosa (p < 0.0001)." (PMID 27486820, 2016). "Moreover high expression of Tyro3 and Mer in tumor tissue significantly shortens CRC patients' survival." (PMID 27486820, 2016). "As a hypothetical example, pan-TAMs TKIs might be expected to target Axl on tumor cells, Mertk on infiltrating M2 macrophages, and Tyro3 on immature DCs, to collectively inhibit cancer growth, polarize macrophages and maximize antigen presentation." (PMID 27916840, 2016). "In CRC patient samples Tyro3 was overexpressed within the tumor." (PMID 27486820, 2016). "As a result, we sought to explore the hypothesis that the balance in expression of the GAS6 receptors Axl and Tyro3 regulates tumor cell proliferation and dormancy." (PMID 23637920, 2013). "In contrast, little if any Tyro3 was expressed in vitro by most tumor cell lines." (PMID 23637920, 2013). "Furthermore, studies have shown that in melanoma, upregulating TYRO3 to limit tumor ferroptosis promotes resistance to α-PD-1/PD-L1 immune checkpoint inhibition, while enhancing tumor ferroptosis by targeting the Wnt/β-catenin-MITF pathway can improve the efficacy of anti-PD-1 immunotherapy." (PMID 40169575, 2025). "Therefore, targeting TYRO3 could interfere with energy generation, hinder proliferation and migration ability, and improve drug resistance of tumor cells." (PMID 37116196, 2023). "Notably, cabozantinib targets MET and the Tyro3/Axl/Mer family of receptor kinases, which may promote an immune environment and make tumor cells more sensitive to immune-mediated killing." (PMID 36982920, 2023). "Therefore, the correlation between TYRO3 expression and tumor metabolic genes was also explored." (PMID 37116196, 2023). "We then found that both the tumor cells and the immune cells could express the ligand, GAS6, while only the dividing tumor cells displayed high expression of the receptor, TYRO3, which indicated the specific activation of the TYRO3 downstream signaling in those cells." (PMID 38110427, 2023).
tumor (continued). "However, there are only a few studies on TYRO3, especially in tumor diagnosis and treatment." (PMID 37116196, 2023). "Notably, a family of receptor tyrosine kinases, Tyro3, Axl, and MerTK receptors (TAM-R) have been described as new regulators of myeloid immune response and as such represent promising therapeutic targets on tumor-associated myeloid cells." (PMID 33101282, 2020). "Moreover, there is versatility in Tyro3 signalling interactions with second messengers through its capability of coupling to cell proliferation and survival and invasion pathways, thus promoting tumour progression profoundly." (PMID 31766614, 2019). "Compared with the normal group, the expression of DDC and SYT11 were remarkably up-regulated in the tumor group, while the expression of GCLM, PSMB7, TYRO3, and AGMAT were remarkably down-regulated in the tumor group." (PMID 38526709, 2025). "TYRO3 expression was rarely detected, while AXL was expressed in myeloid cells, tumor epithelial cells, and CAFs." (PMID 40433916, 2025). "Interestingly, WT and Axl-/- MDSCs were found in both the primary tumor as well as the tumor-draining lymph node (TDLN), but Mertk-/- and Tyro3-/- MDSCs were predominantly in the primary tumor and not in the TDLN, suggesting that the loss of MERTK or TYRO3 attenuates MDSC migration." (PMID 39062902, 2024). "In the BRAF and RNF43 tumours, co-occurring mutations were observed in ACVR2A (FDR-adjusted P = 0.06) in HM tumours, and AKT1 (FDR-adjusted P = 0.03) and TYRO3 (FDR-adjusted P = 0.08) in the nHM tumours." (PMID 39112715, 2024). "The gene AXL, belonging to the Tyro3-Axl-Mer (TAM) receptor tyrosine kinase subfamily, has the ability to enhance tumor advancement and serve as an indicator of unfavorable prognosis." (PMID 38194709, 2024). "Sitravatinib, a receptor tyrosine kinase inhibitor targeting TYRO3, AXL, MERTK receptors, and vascular epithelial growth factor receptor 2, can shift the tumor microenvironment toward an immunostimulatory state." (PMID 36842467, 2023). "The correlation between the TYRO3 expression level in tumor tissues and the overall survival time of CRC patients was considered to determine the potential role of TYRO3 expression in prognosis prediction." (PMID 37116196, 2023). "Data on the role of TYRO3 in macrophage polarization are scarce with one study showing that TYRO3 can inhibit lipopolysaccharide (LPS) and interferon-gamma (IFN-γ)-induced M1 polarization of peritoneal and tumor-derived mouse macrophages." (PMID 38203403, 2023). "When TYRO3 expression was higher than AXL, tumor cells proliferated and, on the other hand, when AXL expression levels exceeded those of TYRO3, the cancer cells remained largely quiescent." (PMID 38203403, 2023). "In this model, AXL expression is weak in macrophages and high in tumor and DCs, whereas MERTK and TYRO3 expression is marginal in carcinoma cells and restricted to macrophages and DCs." (PMID 35572601, 2022). "TAM receptors promote tissue-specific macrophage polarisation into a pro-tumour M2-like phenotype as AXL and TYRO3 regulate phagocytosis in dendritic cells, whereas MERTK do so in the thymus and retina." (PMID 35626092, 2022). "Vice versa, in the four cell lines with strong constitutive activation of TYRO3/Dtk (1889c, PC3, HCC15, and LNCaP), gene silencing with two individual siRNAs resulted in significantly more tumor cell killing upon exposure to sunitinib." (PMID 36230684, 2022). "TYRO3 belongs to the TAM (TYRO3-ABL-MER) family of RTKs, which can regulate tumor cell survival, proliferation, and angiogenesis." (PMID 36230684, 2022). "Sitravatinib (MGCD516), a spectrum-selective receptor tyrosine kinase inhibitor targeting TAM (TYRO3, AXL, MERTK) and split kinase family receptors, has demonstrated preclinical anti-tumor activity and modulation of tumor microenvironment." (PMID 35767205, 2022).
tumor (continued). "Mertk-/-, Axl-/- and Tyro3-/- tumor models were revealed to reduce RTK enzymatic activity, exhibit defective MDSC roles, and display poor tumor migration capacity to tumor-draining lymph nodes (TDLN)." (PMID 36131911, 2022). "Similar to other TAM RTKs, TYRO3 was also shown to activate common oncogenic signaling pathways, such as MEK/ERK and PI3K/AKT, in tumor cells." (PMID 34721022, 2021). "Growth arrest-specific protein 6 can be derived from BMSCs or osteoblasts and plays an important role in the progression of tumor cells dormancy and reactivation by being combined with TAM receptors such as AXL and Tyro3." (PMID 34712663, 2021). "In accordance, Tyro3 expression is increased in HCC patient samples compared to adjacent tissue and is positively correlating with tumor size and augmented levels of AFP and alanine aminotransferase." (PMID 34771611, 2021). "TYRO3, AXL, and MERTK constitute the TAM family of receptor tyrosine kinases, which play important roles in tumor growth, survival, cell adhesion, as well as innate immunity, phagocytosis, and immune-suppressive activity." (PMID 33425754, 2020). "The third promoter of tumor growth whose expression is induced by gal-8 is Gas6, the ligand of the TAM family (Tyro3, Axl, and Mer) of receptor tyrosine kinases." (PMID 32355198, 2020). "In this review, we will discuss the function of TYRO3, AXL and MERTK on all cells in the tumor micro-environment, with a special focus on T cells." (PMID 31664482, 2020). "Consistently, we found that TYRO3 knockdown in SGC7901 cells suppressed tumor growth in vivo, as evidenced by a reduction of tumor mass and tumor volume." (PMID 32018224, 2020). "Tyro3, Axl, and Mertk, collectively called TAM receptors, can activate the expression of PD-L1 in tumor cells, and additionally, IFN-γ secreted by inflammatory cells in the TME is associated with macrophage differentiation." (PMID 32630659, 2020). "It has been shown that Protein S activation of either MerTK or Tyro3 inhibits LPS and IFN-γ induced M1 polarization of peritoneal and tumor-derived mouse macrophages, indicated by decreased expression of M1 marker genes Il1, Il6, Cd86 and Tnf." (PMID 31088471, 2019). "Similarly, the TYRO3 functions that promote cell survival in neurons during cell stress may promote survival of tumor cells under the conditions of nutrient deprivation and hypoxia that are hurdles to tumor growth." (PMID 30501104, 2018). "TYRO3 is expressed in a wide variety of cancer types and mediates downstream signaling through PI3K/AKT, MAPK/ERK and other oncogenic pathways to promote tumor cell survival and proliferation, motility, and EMT." (PMID 30501104, 2018). "AXL and MER are two members of the TAM (TYRO3-AXL-MER) family of receptor tyrosine kinases, which, when activated, can regulate tumor cell survival, proliferation, migration and invasion, angiogenesis, and tumor-host interactions." (PMID 28251492, 2017). "Notably however, both Tyro3 and Mertk become hyperactivated in the presence of phosphatidylserine (PS)-positive liposomes and apoptotic cells, implying that Mertk and Tyro3 may act as “PS sensors” for externalized PS on apoptotic cells and in the tumor microenvironment." (PMID 29176978, 2017). "The preliminary analysis of the surface inhibitory receptors of DCs showed that several receptors, including B7H3, Tim3, CD31, and OX2, were increased in tumour-induced DCs, with a decrease in CD301, FcγRIIA, DCIR, ILT4, and Tyro3." (PMID 28350008, 2017). "Paired tissue analysis in 3 patients identified ARG, AXL, TYRO3 and ZAP70 as increased in tumor relative to adjacent normal." (PMID 28423512, 2017). "Emerging areas of research include modulation of TAM receptors to enhance anti-tumor immunity, mechanisms of resistance to TAM inhibition, and potential roles for TYRO-3 in leukemogenesis." (PMID 27834816, 2016).
tumor (continued). "TYRO3, a TAM family receptor tyrosine kinase, and SDHA, a mitochondrial enzyme involved in succinate metabolism, may contribute to tumor progression and represent emerging therapeutic vulnerabilities." (PMID 41373665, 2025). "TYRO3, a member of the RTK family, is required for tumor cell growth and reproduction." (PMID 40959280, 2025). "Importantly, we report TYRO3 amplification for the first time in SCLC, detected in one-third of cases, suggesting a novel mechanism of tumor progression and a potential therapeutic vulnerability." (PMID 41373665, 2025). "Immunohistochemical (IHC) analysis of tumor tissues confirmed that GAS6 + macrophage co-culture and GAS6 treatment promoted EMT (increased N-cadherin and decreased E-cadherin), which was attenuated by TYRO3 inhibition." (PMID 41034991, 2025). "Ultimately, we found that ECGs presented different profiles across 20 cancer types, with CD47 and TYRO3 more frequently exhibiting copy number increases rather than losses in the majority of tumours, while AXL and HAVCR1 showed a relatively opposite trend." (PMID 40576208, 2025). "Furthermore, TYRO3 has been demonstrated to inhibit ferroptosis, as well as FANCD2, thereby enhancing tumour cell survival." (PMID 40415137, 2025). "After 24 h of co-culture, tumor cell proliferation was significantly enhanced in the GAS6 + macrophage co-culture and GAS6 treatment groups compared to the PBS and GAS6- macrophage co-culture groups, while TYRO3 inhibition suppressed this effect." (PMID 41034991, 2025). "Neither Tyro3 nor macrophage phagocytosis by alternate genetic redundancy accounts for the absence of anti-tumor immunity." (PMID 35969037, 2022). "In particular, the beneficial collaboration between drugs seems to boost immunosurveillance mechanisms in the tumour microenvironment, modulated mainly through simultaneous PD1 blockade and inhibition by cabozantinib of Tyro3/AXL/MER (TAM) receptors and VEGFR1." (PMID 35106125, 2022). "The addition of anti–PD-1 significantly increased lipid ROS in 4T1-P, but not in Tyro3-OE tumor cells, supporting the assumption that TYRO3 suppresses anti–PD-1–induced tumor cell ferroptosis." (PMID 35399527, 2022). "Even mice with simultaneous ablation of Mertk and Tyro3 did not phenocopy the anti-tumor resistance of Mertk-/-V1 mice." (PMID 35969037, 2022). "Thus, apart from impairing VEGF signalling, cabozantinib inhibits a variety of receptor tyrosine kinases including MET and TAM kinases (TYRO3, AXL, MER) involved in tumour growth, metastasis, and therapeutic resistance with a role in immunosuppression." (PMID 35106125, 2022). "As many cancer types express MERTK and TYRO3 as well as their ligand PROS1, we hypothesized that tumor cells may exploit the TAM-receptor-dependent regulation of osteoblasts and inhibit their function via MERTK39–45." (PMID 36509738, 2022). "AXL is one of the TAM (Tyro3/Axl/Mer) receptor families, the intracellular segment of AXL has kinase activity and can participate in the transmission of various signaling pathways in normal cells and tumor cells." (PMID 36408274, 2022). "It was revealed that TYRO3 prohibited the ferroptosis of tumor cells induced by anti-PD-1/PD-L1 via the AKT/NRF2 axis and amplified a pro-tumor microenvironment by downgrading the ratio of M1/M2 macrophages, consequently contributing to anti-PD-1/PD-L1 treatment." (PMID 36335094, 2022). "It has been previously reported that many tumor cells and immunosuppressive cells within the TME upregulate the expression of receptor tyrosine kinases Tyro3, Axl, and Mertk (collectively known as TAM receptors), which can interact with PS to stimulate the expression of PD-L146." (PMID 32111835, 2020). "Axl, a TAM (Tyro3/Axl/Mer) family receptor tyrosine kinase (RTK), was recently shown to be highly expressed in radio-resistant tumors, and Axl inhibition in combination with radiotherapy or other anticancer therapies elicited anti-tumor responses." (PMID 31384397, 2019).
tumor (continued). "No or weak TYRO3 staining was observed on urothelium from histologically normal tissue adjacent to the tumour (NAT), whereas TYRO3 was highly expressed by tumour epithelial cells and not by stromal cells in both NMIBCs and MIBCs." (PMID 30765874, 2019). "In addition, the tumor suppressor miR-7 has been found to promote sorafenib sensitivity in HCC cells through silencing expression of TYRO3, a member of TYRO3-AXL-MER family of receptor tyrosine kinases." (PMID 31651347, 2019). "Merestinib is a potent inhibitor of NTRK, it also targets additional kinases such as the TAM receptors (AXL, MERTK, and TYRO3), and MKNK1 and MKNK2, which may also contribute to anti-tumor growth." (PMID 30885237, 2019). "Thus, tumor cells produce PROS1 in response to pro-inflammatory M1 cytokines and PROS1 stimulates TYRO3 and MERTK on macrophages to promote an anti-inflammatory M2 phenotype, thereby repressing the innate immune response in the tumor microenvironment." (PMID 30501104, 2018). "TYRO3 is a member of the TAM (TYRO3, AXL, MERTK) family of transmembrane receptor tyrosine kinases, which share overlapping functions in tumorigenesis and suppression of anti-tumor immunity." (PMID 30501104, 2018). "It is important to point out that while merestinib is a potent inhibitor of NTRK, it also targets additional kinases such as the TAM receptors (AXL, MERTK, and TYRO3), and MKNK1 and MKNK2, which may also contribute to anti-tumor growth." (PMID 29568395, 2018). "To determine if proteins were expressed specifically in neoplastic cells, we examined the expression of Akt (pT308), Tyro3, and PAI-1 by immunohistochemistry using the corresponding paraffin-embedded patient samples from six cases that contained all three tumor regions." (PMID 29142297, 2017). "Similarly, TAM receptors (Tyro3, Axl, and MerTK), the cognate receptors of GAS6 on apoptotic cells, are also expressed on TAMs and skew polarization toward a pro-tumor M2-like phenotype, participating in immune homeostasis and tumor progression." (PMID 38274812, 2023). "Therefore, TYRO3 expression inhibition in drug-resistant cells may reduce ENO1 expression, down-regulating the proliferation and migration of tumor cells by restricting glucose utilization and partial ATP production." (PMID 37116196, 2023). "Thus, inhibiting the expression of TYRO3 in H-DR and T-DR could promote the expression of E- Cadherin and reduce the expression of Vimentin, suggesting the inhibition of the EMT process of tumor cells." (PMID 37116196, 2023). "Furthermore, in a syngeneic BALB/c mouse model, anti-PD-1 treatment significantly reduced tumor growth and extended survival in mice bearing 4T1-P (anti–PD-1–responsive) tumors, but not in those bearing Tyro3-OE (Tyro3-overexpressing) tumors." (PMID 35399527, 2022). "Given that intra-tumoral Tyro3, Mer, and Axl signaling contributes to tumor growth, immune evasion, drug resistance, proliferation, and metastasis, TAM RTKs represent an important drug candidate to simultaneously target both malignant cells and immune cells in order to enhance anti-tumor immunity." (PMID 33807608, 2021). "Consistent with the results of mRNA analysis, TYRO3 levels in almost all tumours were higher than those in normal urothelium and vesical muscle samples, whereas AXL levels were higher than those in the urothelium in only a few tumours and this protein was abundant in the vesical muscle." (PMID 30765874, 2019). "In contrast, TYRO3 expression was not increased when the tumor cells were implanted by cardiac injection, suggesting selection for high TYRO3 expression during the initial steps of metastasis in this model and consistent with the demonstrated roles for TYRO3 in EMT." (PMID 30501104, 2018). "When evaluating differences between the tumours, we identified Axl, a TAM (Tyro3/Axl/Mer) family receptor tyrosine kinase (RTK), to be highly expressed in the radioresistant tumour but not in the responsive tumour." (PMID 28008921, 2016).